ZNF181 (zinc finger protein 181)
Description:
May be involved in transcriptional regulation.
Synonyms: HHZ181; MGC44316
Tractability: PROTAC: UniProt records ubiquitination sites on it; ubiquitination databases record sites on it.
Gene: Protein-coding gene on chromosome 19 (34,734,155 to 34,745,386, forward strand). Ensembl gene ENSG00000197841.
Subcellular location: Nucleus
Subcellular location (Human Protein Atlas): Nucleoplasm
Gene Ontology:
Molecular function: DNA-binding transcription factor activity, RNA polymerase II-specific; RNA polymerase II cis-regulatory region sequence-specific DNA binding
Biological process: regulation of transcription by RNA polymerase II; regulation of DNA-templated transcription
Cellular component: nucleus
Genetic constraint (gnomAD): Loss-of-function variants: 9 observed, 11.78 expected, observed/expected ratio (o/e) 0.76, 90% interval 0.46 to 1.33. The upper end of that interval is the gene's LOEUF score, 1.33, which puts it in group 5 of 6, group 1 being the genes least tolerant of losing a copy. Missense variants: 542 observed, 682.67 expected, observed/expected ratio (o/e) 0.79, 90% interval 0.74 to 0.85. Synonymous variants: 202 observed, 224.4 expected, observed/expected ratio (o/e) 0.9, 90% interval 0.8 to 1.01.
Homologues: Orthologues: chimpanzee ZNF181 (98% identical), macaque ZNF181 (93% identical), zebrafish si:dkey-89b17.4 (24% identical), zebrafish znf646 (23% identical), Drosophila melanogaster CG18011 (20% identical), zebrafish znf576.1 (19% identical), zebrafish zgc:66472 (17% identical), Caenorhabditis elegans ztf-15 (16% identical), Drosophila melanogaster CG1602 (16% identical), Drosophila melanogaster mld (14% identical), Drosophila melanogaster CG30020 (14% identical), Drosophila melanogaster az2 (14% identical), and 7 more. Paralogues in human: ZNF302 (63% identical), ZNF160 (47% identical), ZNF84 (46% identical), ZNF91 (46% identical), ZNF184 (45% identical), ZNF107 (44% identical), ZNF208 (44% identical), ZNF569 (44% identical), ZNF420 (43% identical), ZNF99 (43% identical), ZNF347 (43% identical), ZNF729 (41% identical), and 24 more.